G6PD (glucose-6-phosphate dehydrogenase)
Diseases named in the same sentence as G6PD in open-access papers (continued):
Sharing a sentence is not in itself a finding about the gene and the disease.
glioma (continued). "Metformin regulates GBM cell lines through the circadian gene PER2 and the SIRT2/G6PD signaling pathway in a PER2-dependent manner, as well as through synergies with the radiotherapy sensitivity of glioma cells." (PMID 40166471, 2025). "We also explored the perturbation effects of these genes which suggested that the importance of DPEP1, G6PD, GGT1, GGT5, IDH1, and NFE2L2 for glioma cell survival." (PMID 38819225, 2024). "Erasing the m6A methylation of glucose-6-phosphate dehydrogenase (G6PD) enhances its stability and then ALKBH5 promotes G6PD translation and activates the pentose phosphate pathway (PPP) to induce the proliferation of glioma cells." (PMID 38072944, 2023). "The gene expression levels of H6PD, G6PD, ADSL, APRT, GMPS, PRPS1, and IMPDH1 in human glioma patients were significantly higher than those in the control group." (PMID 33723244, 2021). "Taken together, upregulation of G6PD/H6PD in the PPP plays an important role in acidic-driven purine metabolic reprogramming and confers a predilection toward glioma progression." (PMID 33723244, 2021). "HSPB1 activates G6PD through SIRT2 to sustain cellular NADPH and pentose production in glioma cells." (PMID 31500396, 2019). "Decreased expression of both G6PD and TKT was observed in glioma cells upon transfection with TERT dominant-negative construct or siRNA-mediated knock-down of TERT." (PMID 27148686, 2016). "HSPB1 activates G6PD by promoting SIRT2-mediated G6PD deacetylation, thereby contributing to glioma cell survival and proliferation." (PMID 27711253, 2016). "In conclusion, our study revealed that HSPB1-mediated G6PD activation sustained cellular NADPH and pentose levels, and promoted glioma cell proliferation and survival." (PMID 27711253, 2016). "ALKBH5 demethylates the G6PD transcript and enhances its mRNA stability, thereby promoting G6PD translation and activating the pentose phosphate pathway (PPP), consequently enhancing glioma cell proliferation." (PMID 40469294, 2025). "Thus, Chr-A prevented the utilization of glucose by glioma cells through the inhibition of HK2 and G6PD." (PMID 39330272, 2024). "Specifically, malic acid levels, the expression level of G6PD and NADPH production were significantly reduced by Chr-A, indicating that Chr-A may mediated oxidative stress in glioma cells through metabolic reprogramming." (PMID 39330272, 2024). "Our findings indicate that targeting G6PD/H6PD, which are closely related to glioma patient survival, may serve as a promising therapeutic target for improved glioblastoma therapeutics." (PMID 33723244, 2021). "Moreover, this overexpression is related to the grade of the tumor; the levels of expression of G6PD were in the range of 5 to 245-fold in CNS WHO grade 1 and 2 gliomas compared to CNS WHO grade 3 and 4 gliomas, with a range of 2197 to 4946-fold." (PMID 34573317, 2021). "The rate-limiting enzyme of the pentose-phosphate pathway, glucose-6-phosphate dehydrogenase (G6PD) was expressed at higher levels in IDH1WT glioma, but only in LGG and not glioblastoma." (PMID 28467784, 2017). "In glioma, a central nervous system malignancy, overexpression of ALKBH5 increases the transcriptional region m6A demethylation and thus enhances the mRNA stability of glucose-6-phosphate dehydrogenase (G6PD), the rate-limiting enzyme of the pentose phosphate pathway (PPP)." (PMID 37007161, 2023). "Specifically, ALKBH5 demethylates the transcript of glucose-6-phosphate dehydrogenase (G6PD), the rate-limiting enzyme of the pentose phosphate pathway (PPP), and enhances its mRNA stability, thus promoting oxidative PPP flux and stimulating the aggravation of glioma." (PMID 35063010, 2022).
glioma (continued). "Very recently, HSPB1 was reported to activate glucose 6-phosphate dehydrogenase (G6PD), the rate-limiting enzyme in pentose phosphate pathway, in response to oxidative stress (.These observations indicate that HSPB1 possibly regulates the metabolism of glioma cells." (PMID 27711253, 2016). "Besides, HSPB1 activates G6PD to sustain cellular NADPH and pentose production in glioma cells." (PMID 27711253, 2016). "Despite extensive evidence showing upregulation of G6PD expression and activity across various tumors, its regulation through acetylation/deacetylation by KAT9 and SIRT2 has not yet been studied in hypoxic glioma cells." (PMID 41009654, 2025). "Collectively, these results indicate that, under acidic conditions, G6PD and H6PD may play important roles in metabolic remodeling of GSCs but not differentiated glioma cells." (PMID 33723244, 2021). "Similarly, knockdown of either G6PD or HSPB1 sensitized glioma cells to oxidative reagents (H2O2 or diamide), but no additive effect was found in HSPB1- and G6PD-knockdown cells." (PMID 27711253, 2016).
falciparum malaria (30 papers, 2005 to 2025). "The present study aims to investigate the prevalence of HBB (chr11) and G6PD (chrX) deficiencies polymorphisms among Senegalese populations and their associations with the risk for severe Plasmodium falciparum malaria occurrence." (PMID 35811813, 2022). "First, the degree of enzyme deficiency with G6PD Med is substantially greater than in the common African A− variant, which has been the main genotype studied previously in falciparum malaria studies." (PMID 33543710, 2021). "It has been shown that G6PD deficient red cells inhibit the growth of Plasmodium falciparum malaria in vitro even when mixed with G6PD normal cells." (PMID 33925963, 2021). "MB is safe for the treatment of uncomplicated falciparum malaria, even in G6PD deficient African children." (PMID 16179085, 2005). "The relatively mild West African G6PD A− variant (10% to 60% G6PD activity), found in 39.3% of the G6PD-deficient Amazonians, is associated with a significant reduction in the risk of severe falciparum malaria in both male hemizygotes and heterozygous females in Africa." (PMID 36634044, 2023). "This may be one possible explanation the observed G6PD associated protect from falciparum malaria in Africa." (PMID 28382932, 2017). "However, there is conflicting information on the effect of G6PD variant on falciparum malaria." (PMID 32646433, 2020). "G6PD 563c.C>T was detected in four of 110 patients with falciparum malaria and in two of 100 healthy blood donors." (PMID 29065882, 2017). "G6PD c.563C>T was observed in four of 110 patients with falciparum malaria and in two of 100 healthy donors." (PMID 29065882, 2017). "For example, in Africa, G6PD A-type offers relative protection against falciparum malaria in hemizygous males and to some extent in heterozygous females." (PMID 29065882, 2017). "During the study period 141 falciparum malaria patients had their G6PD status assessed by FST and/or genotyping." (PMID 28356147, 2017). "The recently concluded dose-finding trial in children aged 1 to 10 years with uncomplicated falciparum malaria and normal G6PD enzyme function provides encouraging complementary information to support research in G6PD-deficient individuals." (PMID 25887344, 2015). "Again, non-falciparum malaria, P. ovale and P. malariae were more prevalent in G6PD B variants with no infections identified in individuals with the A-A- and AA- variants." (PMID 34570821, 2021). "The degree of protection conferred by G6PD Med against P. vivax illness estimated in this study is large; it is similar in magnitude to the well-described protection conferred by Hb AS (sickle cell heterozygotes) against falciparum malaria." (PMID 33543710, 2021). "Falciparum malaria, the selective force responsible for the expansion of class 2 G6PD variants (typically, G6PD Mediterranean), was never present in Northern Europe." (PMID 17637841, 2007). "During treatment of 181 children, including 24 G6PD-deficient children with uncomplicated falciparum malaria in Burkina Faso, no drug related SAEs and, particularly, no cases of severe haemolysis were observed." (PMID 16179085, 2005). "To recapitulate, we inferred from this analysis that G6PD deficiency may not generally protect against uncomplicated falciparum malaria, P. vivax, or P. malariae." (PMID 28382932, 2017). "G6PD status was assessed via a combination of fluorescent spot testing (FST) and genotyping in 141 Bengali patients admitted with falciparum malaria to two centres in Chittagong Division from 2012 to 2014." (PMID 28356147, 2017). "This study's findings indicate that using SLD-PQ in combination with ACT is safe for uncomplicated falciparum malaria regardless of the patient’s G6PD status in Ethiopian settings." (PMID 38997771, 2024). "falciparum malaria except that in a P. ovale positive patient due to lack of glucose-6-phosphate dehydrogenase (G6PD) enzyme activity." (PMID 29402283, 2018).
falciparum malaria (continued). "The purpose of this study was to evaluate the frequency of G6PD c.563C>T (G6PD Mediterranean) in male individuals with and without falciparum malaria." (PMID 29065882, 2017). "The present evidence supports a broader use of low dose primaquine without G6PD testing for the treatment and elimination of falciparum malaria." (PMID 27010542, 2016).
Insulin resistance (29 papers, 2013 to 2025). Increased resistance towards insulin, that is, diminished effectiveness of insulin in reducing blood glucose levels. "Increased pentose phosphate pathway in GDM mothers was associated with adiposity and insulin resistance as glucose-6-phosphate dehydrogenase enzymes promote dysfunction of pancreatic Beta-cell and apoptosis." (PMID 38684759, 2024). "Similar findings were reported by Wang, who linked G6PD overexpression in Wistar rats, induced by a high-fat diet, to enhanced insulin resistance." (PMID 38203517, 2023). "Altered G6PD and G6PD activities in PPP are associated with insulin resistance in peripheral tissues and there is relatively little research on their relationships in the brain." (PMID 37396164, 2023). "The overexpression of G6PD has been reported to be protective in the development of some age-associated conditions in mice, such as insulin resistance, neuromuscular impairment, lower DNA oxidation levels and frailty." (PMID 36835034, 2023). "Lipogenic enzymes FAS, G6PD, and CPT are involved in the biosynthesis of cholesterol and fatty acid, and increased FAS and G6PD activities have been associated with lipid dysregulation, insulin resistance, and elevated triglyceride levels." (PMID 33552386, 2021). "In our quantitative RT-PCR array experiments, expression of hepatic G6PD, which has been reported to be associated with insulin resistance, markedly decreased in the HFA group." (PMID 28870184, 2017). "These G6PD-deficient mice exhibit glucose and insulin tolerance as well as reduced insulin signaling, suggesting that G6PD deficiency is associated with an improvement in insulin resistance." (PMID 31500396, 2019). "Jiang and colleagues demonstrated that overexpression of G6PD in C2C12 mouse myoblast cell lines results in insulin resistance." (PMID 38203517, 2023). "Abnormal G6PD status mediates insulin resistance through oxidative stress in adipose tissue found in obese mice." (PMID 31500396, 2019). "In the present study, G6PD was predicted to be regulated by miR-700-5p, which may protect against insulin resistance, while G6PD upregulation may lead to oxidative stress and functional defects in the liver, heart, and pancreatic β-cells." (PMID 39823117, 2025). "Park and his team found that G6PD overexpression in adipocytes upregulates insulin resistance." (PMID 38203517, 2023). "Since up-regulation of G6PD impaired insulin signaling response, we next explored whether high-fat treatment could result in insulin resistance by increasing G6PD." (PMID 35806430, 2022). "Irrespective of the mechanism behind the reduced ATP production (or increased ATP consumption), an increase in G6PD activity has been related to increased lipid dysfunction and insulin resistance, thus landing support to our observation and its experimental and clinical relevance." (PMID 25905030, 2014). "Indeed, increased expression of G6pd promotes hepatic steatosis and insulin resistance, but in the MI group, G6dp expression is decreased, which could be ameliorating this effect." (PMID 34684533, 2021). "The results in addition showed insulin resistance, hyperinsulinemia, hyperandrogenism and oxidative stress as well as a significant increase in inflammatory biomarkers (NF-kB/TNF- and IL-6), with a significant decrease in TG, TC, FFA, GSH and G6PD in the adipose tissue of PCOS animals." (PMID 36071485, 2022).
melanoma (29 papers, 2013 to 2025). A malignant, usually aggressive tumor composed of atypical, neoplastic melanocytes. "Protein expression at a STAT3/5 ratio and a phosphorylated STAT3/5 ratio is reduced in G6PD-deficient melanoma cells." (PMID 37185731, 2023). "Fas, a death domain-containing protein regulating programmed cell death, is highly expressed in G6PD-deficient melanoma cells." (PMID 31500396, 2019). "The protein expression of the STAT3/5 ratio and the phosphorylated STAT3/5 ratio are decreased in G6PD-deficient melanoma cells." (PMID 31500396, 2019). "The lowest G6PD activity was observed in the A375-G6PD∆ cell group (P < 0.01), demonstrating the association of G6PD with melanoma formation and growth in nude mice." (PMID 23693134, 2013). "Melanomas with mutated glucose-6-phosphate dehydrogenase (G6PD), a key enzyme in the pentose phosphate pathway, were found to have higher levels of oxidative stress, highlighting G6PD inhibition as a potential therapeutic target." (PMID 39519202, 2024). "Additionally, they showed that during metastasis, melanoma cells become more dependent on G6PD, likely due to increased oxidative stress associated with metastasis." (PMID 39796677, 2024). "Loss of G6PD function thus reduces the levels of TCA cycle intermediates in some melanomas." (PMID 35110412, 2022). "We wondered whether G6PD mutant melanomas might compensate for the loss of G6PD function by increasing NADPH production through other mechanisms." (PMID 35110412, 2022). "To test whether G6PD deficiency affected subcutaneous tumor growth or metastasis, we subcutaneously transplanted 100 G6PD mutant or control melanoma cells into NSG mice." (PMID 35110412, 2022). "In G6PD-deficient melanoma cells, the expression of Bcl-2 and Bcl-xL is significantly reduced." (PMID 31500396, 2019). "HEM (human epidermal melanocyte) cells and human melanoma cells with the wild-type G6PD gene (A375-WT), G6PD deficiency (A375-G6PD∆), G6PD cDNA overexpression (A375-G6PD∆-G6PD-WT), and mutant G6PD cDNA (A375-G6PD∆-G6PD-G487A) were subcutaneously injected into 5 groups of nude mice." (PMID 23693134, 2013). "Recently, multiple studies have demonstrated that elevated G6PD levels can promote cancer progression in numerous tumor types, including melanoma, leukemia, and BLCA." (PMID 37958478, 2023). "A decrease in the G6PD level in melanoma cell lines leads to a decrease in phosphorylated STAT5, which is important for uncontrolled cell growth." (PMID 37185731, 2023). "Nonetheless, the nonnormalized fractional enrichments tended to be higher in the G6PD mutant as compared to control melanomas." (PMID 35110412, 2022). "Glutaminase inhibition thus increased ROS levels to a greater extent in G6PD mutant as compared to control melanoma cells." (PMID 35110412, 2022). "The data suggest that melanoma cells become more dependent upon G6PD during metastasis, consistent with the increase in oxidative stress during metastasis." (PMID 35110412, 2022). "That same group also reported that G6PD works in tandem with NOX4 to activate STAT3 signaling to promote melanoma proliferation and avoid cell cycle arrest." (PMID 35326683, 2022). "Our results show that melanoma cells have redundant and layered protection against oxidative stress: reduced G6PD function led to compensatory up-regulation of glutaminolysis and malic enzyme activity." (PMID 35110412, 2022). "We performed metabolomic analysis on primary subcutaneous tumors formed by the G6PD mutant as compared to control melanoma cells." (PMID 35110412, 2022). "Levels of ROS tended to be significantly higher in subcutaneous tumors formed by the G6PD mutant as compared to control melanoma cells based on both CellRox green and CellRox red staining." (PMID 35110412, 2022). "G6PD mutant melanomas compensated for this increase in oxidative stress by increasing malic enzyme activity and glutamine consumption." (PMID 35110412, 2022).